SRSF6 (serine and arginine rich splicing factor 6)
Diseases named in the same sentence as SRSF6 in open-access papers (continued):
Sharing a sentence is not in itself a finding about the gene and the disease.
diabetes (4 papers, 2019 to 2022). "SRSF6 abundance has been repeatedly associated with cancer, liver disease, and diabetes and recent work has identified several roles for SRSF6 in mitochondrial function and cell death." (PMID 36409059, 2022). "In the pancreatic β-cells, SRSF6 expression is regulated by the diabetes susceptibility gene GLIS3, which encodes an important transcription factor for β-cell development and maintenance of the differentiated phenotype." (PMID 33376132, 2021). "Here, we investigated the mechanisms of splicing regulation by the splicing factor SRSF6 in the human pancreatic β-cell line EndoC-βH1 and its impact on diabetes susceptibility genes." (PMID 33376132, 2021). "We found that SRSF6 KD significantly affected 28 AS events in well-documented diabetes susceptibility genes (five T1D susceptibility genes, and 17 T2D susceptibility genes)." (PMID 33376132, 2021). "This combined approach unveiled how SRSF6 specifically recognizes its binding sites and promotes exon inclusion, thereby regulating the splicing of diabetes susceptibility genes." (PMID 33376132, 2021). "SRSF6 has also been implicated in cancer, skin hyperplasia, and diabetes." (PMID 33905374, 2021). "In pancreatic β-cells, the expression of the splicing factor SRSF6 is regulated by GLIS3, a transcription factor encoded by a diabetes susceptibility gene." (PMID 33376132, 2021). "Taking into account that SRSF6 was initially found as a downstream target of the diabetes candidate gene GLIS3 in the rat cell line Ins1E, we tested for this association in human cells." (PMID 33376132, 2021). "We previously found that SRSF6 regulated AS of many genes involved in central β-cell functions, such as insulin secretion, evidencing its role as key splicing regulator for β-cells and thus suggesting a link to diabetes." (PMID 33376132, 2021). "Moreover, we showed that SRSF6, which is regulated by the diabetes candidate gene GLIS3, modulates the splicing of other diabetes susceptibility genes, suggesting the presence of an AS-regulated network with a putative impact on diabetes risk." (PMID 33376132, 2021). "However, the WT1-SRPK1 signaling pathway is not the only pathway known to regulate VEGF-A splicing; SRSF6, which promotes distal splice site selection in exon 8 of VEGF-A (increasing VEGF-Axxxb expression) has recently been shown to be down-regulated in diabetes." (PMID 30865689, 2019).
acute lymphoblastic leukemia (3 papers, 2021 to 2022). Leukemia with an acute onset, characterized by the presence of lymphoblasts in the bone marrow and the peripheral blood. "Zn(2+)-dependent phosphorylation of SRSF6 has previously been associated with apoptosis via generation of BIM-S and ubiquitin-mediated control of SRSF6 protein levels has been linked to exon skipping in T cell acute lymphoblastic leukemia." (PMID 36409059, 2022). "SRSF6 is also essential for T-cell acute lymphoblastic leukemia (T-ALL) cell proliferation and cell cycle progression." (PMID 34917618, 2021).
Huntington disease (3 papers, 2015 to 2023). Huntington disease (HD) is a rare neurodegenerative disorder of the central nervous system characterized by unwanted choreatic movements, behavioral and psychiatric disturbances and dementia. "The microtubule binding protein 2 (MAP2) was found to be altered in Huntington disease (HD) due to its alternative splicing expression mediated by SRSF6." (PMID 37904233, 2023). "We used the zQ175 knockin model of Huntington’s disease to investigate the effect of heterozygous Srsf6 knockout on incomplete splicing." (PMID 32820193, 2020). "Therefore, heterozygous Srsf6+/− mice were bred to the zQ175 knockin mouse model of Huntington’s disease to examine the effect of decreasing SRSF6 to 50% of wild type levels." (PMID 32820193, 2020). "Therefore, we set out to test this hypothesis, by manipulating SRSF6 levels in Huntington’s disease models in which an expanded CAG repeat had been knocked in to the endogenous Htt gene." (PMID 32820193, 2020). "In order to validate this hypothesis in vivo, we generated Srsf6 knockout mice and demonstrated that a 50% reduction in the levels of SRSF6 did not alter the production of the Httexon1 transcript in brain regions from the zQ175 knockin mouse model of Huntington’s disease." (PMID 32820193, 2020). "We conclude that SRSF6 is not required for the incomplete splicing of HTT in Huntington’s disease." (PMID 32820193, 2020).
ovarian carcinoma (3 papers, 2021 to 2022). A malignant neoplasm originating from the surface ovarian epithelium. "More studies in larger cohorts are required to determine the association between SRSF6 expression and ovarian cancer." (PMID 34917618, 2021). "Therefore, selectively targeting hnRNPLL, SRSF1, and SRSF6 may usher in an important new era of ovarian cancer treatment." (PMID 34244494, 2021). "However, another study showed that the expression level of SRSF6 is not significantly superior to normal controls in a small cohort of patients with ovarian cancer." (PMID 34917618, 2021).
skin cancer (3 papers, 2021 to 2022). "SRSF6 is significantly overexpressed in a set of subtypes of skin cancer, including basal-cell carcinoma, squamous-cell carcinoma, and malignant melanoma." (PMID 34917618, 2021). "In skin cancer, SRSF6 promoted exon 10-15 inclusion of Tnc (extracellular-matrix protein tenascin C) gene, which can promote cell migration through its isoform with 10–15 exons." (PMID 34917618, 2021). "SRSF6 is a proto-oncogene often overexpressed in human skin cancer." (PMID 33622363, 2021).
systemic sclerosis (3 papers, 2021 to 2025). A chronic disorder, possibly autoimmune, marked by excessive production of collagen which results in hardening and thickening of body tissues. "Besides cancer, SRSF6 has been associated with numerous human diseases, such as pleural fibrosis, Huntington’s disease, Alzheimer’s disease, diabetes, and systemic sclerosis." (PMID 34917618, 2021). "Previously, it was reported that SRSF6 participated in fibrosis in patients with systemic sclerosis." (PMID 33905374, 2021). "SRSF6 binds to a 35-nucleotide motif in exon 8 and promotes the usage of distal acceptor site and VEGF165b expression, which was further confirmed in systemic sclerosis patients." (PMID 34917618, 2021).
anaplastic thyroid cancer (2 papers, 2025). "In anaplastic thyroid cancer, NSUN2 regulates SRSF6 splicing to enhance UAP1 and ABC transporter function, inducing multidrug resistance reversible by NSUN2 targeting." (PMID 41399527, 2025). "In anaplastic thyroid cancer, NSUN2 regulates SRSF6 splicing to induce multidrug resistance." (PMID 41399527, 2025).
cervical cancer (2 papers, 2021 to 2022). A primary or metastatic malignant neoplasm involving the cervix. "SRSF6 has been demonstrated to contribute to the regulation of alternative splicing in cervical cancer patients." (PMID 35711821, 2022). "Elucidating the functional impact of SRSF6 in alternative splicing of DNA damage genes could offer a target for cervical cancer therapy." (PMID 33498485, 2021).
chronic obstructive pulmonary disease (2 papers, 2022 to 2023). A chronic and progressive lung disorder characterized by the loss of elasticity of the bronchial tree and the air sacs, destruction of the air sacs wall, thickening of the bronchial wall, and mucous accumulation in the bronchial tree. "Moreover, since a recent study identified indacaterol, a chronic obstructive pulmonary disease (COPD) treatment, as an SRSF6 protein inhibitor, we targeted this protein with this molecule and studied the effect of its inhibition on cell migration." (PMID 37904233, 2023).
melanoma (2 papers, 2015 to 2021). A malignant, usually aggressive tumor composed of atypical, neoplastic melanocytes. "However, SRSF6 overexpression might induce apoptosis by increasing BimS in melanoma cell line." (PMID 34917618, 2021).
neuroblastoma (2 papers, 2015 to 2025). Neuroblastoma (NB) is the most common solid, extracranial childhood tumor. "Furthermore, SRSF6 inhibited the expression of the most potent apoptotic isoform BimS by inhibiting the Bim exon 3 and exon 4 skipping in human neuroblastoma." (PMID 40712780, 2025).
type 2 diabetes (2 papers, 2021 to 2024). "Among the commonly down-regulated transcripts, we found enrichment in SRSF6-regulated and type 2 diabetes pathways, pointing to SRSF6-mediated splicing modifications in IFNα-treated EndoC-βH1 cells." (PMID 38081640, 2024). "SRSF6 silencing modulates splicing of genes involved in beta cell apoptosis, JNK signalling, insulin secretion, and type 2 diabetes." (PMID 38081640, 2024).
asthma (1 paper, 2018). "Significant differences in the expression of SRSF1 and SRSF6 were observed between ASM from horses with asthma in exacerbation, when compared to controls." (PMID 30350466, 2018). "For instance, there was a twofold increase on average in the expression of SRSF1 and SRSF6 during exacerbation of equine asthma when compared to controls (P = 0.008)." (PMID 30350466, 2018).
Azoospermia (1 paper, 2017). Absence of any measurable level of sperm,whereby spermatozoa cannot be observed even after centrifugation of the semen pellet. "There are only several publications about the SRSF6 gene – it is proposed as a candidate gene for colorectal tumors and is associated with an increased risk of nonobstructive azoospermia." (PMID 28796977, 2017).
bone marrow failure (1 paper, 2024). "The role of SRSF proteins in regulating mitochondrial activity has already been shown for SRSF6, but SRSF4 altered expression has never been reported as a cause of bone marrow failure." (PMID 38396760, 2024).
COVID-19 (1 paper, 2022). A disease caused by infection with severe acute respiratory syndrome coronavirus 2. "Specifically, two small nuclear ribonucleoprotein U5 subunits (SNRNP40 and SNRNP200) and multiple splicing factors (e.g., HNRNP A0, A2B1, A3, DL, F, H1, H2, L, LL, R, U, UL1, UL2 and SRSF6) were significantly under-expressed in the COVID-19 patients." (PMID 35421082, 2022).
cystic fibrosis (1 paper, 2020). Autosomal recessive disorder caused by pathogenic variants in the CFTR gene (cystic fibrosis transmembrane conductance regulator), which encodes a chloride and bicarbonate channel expressed in epithelial cells, and follow the diagnosis criteria. "For example, SRSF1 (SF2/ASF), SRSF4 (SRp75), SRSF5 (SRp40), and SRSF6 (SRp55) are able to bind an ISS located in the intron 9 of the CFTR transcript and to skip the exon 9 causing the production of a nonfunctional protein associated with cystic fibrosis development." (PMID 32596243, 2020).
Down syndrome (1 paper, 2022). "Phosphorylation of SRSF6 by DYRK1A promotes the inclusion of exon 5 into TNNT2 transcripts, and increased levels of phosphorylated SRSF6 were detected in myocardium from subjects with Down syndrome." (PMID 35596909, 2022).
Fanconi anemia (1 paper, 2024). Fanconi anemia (FA) is a hereditary DNA repair disorder characterized by progressive pancytopenia with bone marrow failure, variable congenital malformations and predisposition to develop hematological or solid tumors. "Interestingly, mitochondrial dysfunction has already been shown after the loss of SRSF6 and has also been reported in other cMF syndromes (Pearson, Fanconi anemia (FA), Schwachman–Diamond Syndrome (SDS))." (PMID 38396760, 2024).
fragile X syndrome (1 paper, 2022). A genetic syndrome caused by mutations in the FMR1 gene which is responsible for the expression of the fragile X mental retardation 1 protein. "This set of genes included cancer oncogenes (CMYC, CKIT, BCL2, KRAS) and genes associated with different cancer types (ADAM12, ALOX5, SRSF6, VEGF12) as well as FMR1, associated with fragile X syndrome (OMIM: 300624), and SNX12, which is associated with neurodegenerative diseases." (PMID 35573091, 2022).
head and neck squamous cell carcinoma (1 paper, 2025). A squamous cell carcinoma that arises from any of the following anatomic sites: lip and oral cavity, nasal cavity, paranasal sinuses, pharynx, larynx, and salivary glands. "In this study, we reported a positive feedback loop between SRSF6 and FTO, which helped head and neck squamous cell carcinoma (HNSC) cells resist ferroptosis and promoted HNSC progression." (PMID 40712780, 2025).
leukemia (1 paper, 2021). A malignant (clonal) hematologic disorder, involving hematopoietic stem cells and characterized by the presence of primitive or atypical myeloid or lymphoid cells in the bone marrow and the blood. "By controlling exon skipping, SRSF6 is critical for leukemia cells survival." (PMID 33622363, 2021).
liver cancer (1 paper, 2023). An epithelial or non-epithelial malignant neoplasm that arises from the liver. "This is in opposition with its unfavorable prognostic marker status in renal and liver cancers where it is a high expression of SRSF6 which is related to a lower survival rate." (PMID 37904233, 2023). "SRSF6 is considered as an unfavorable prognostic marker in renal and liver cancer." (PMID 37904233, 2023).
metastatic tumors (1 paper, 2022). "Serine/arginine-rich splicing factor 6 (SRSF6) is highly expressed in the cancer tissues of patients with metastatic tumors and is induced by TGF-β1 via suppressing SRSF6 repressing lncRNA LINC01133." (PMID 35736633, 2022).
Myotonia (1 paper, 2025). An involuntary and painless delay in the relaxation of skeletal muscle following contraction or electrical stimulation. "Interestingly, several splicing factors including Srsf6, Prpf39, Rbm7, Tra2b, Rbfox2, and Hnrnpu, exhibited alternative splicing in Mbnl1−/− mice with myotonia, but not in those without." (PMID 41000779, 2025).
osteosarcoma (1 paper, 2022). A usually aggressive malignant bone-forming mesenchymal neoplasm, predominantly affecting adolescents and young adults. "Based on the findings of this study, the role of ZFAS1 in osteosarcoma cells proliferation and metastasis was established through the stabilization of alternative splicing factor SRSF6." (PMID 35184675, 2022).
Pleural effusion (1 paper, 2021). The presence of an excessive amount of fluid in the pleural cavity. "SRSF6 protein and mRNA levels were explored in clinical samples and found to be significantly higher in cells from patients TBPE than that from transudative pleural effusion (TPE)." (PMID 33905374, 2021).
renal fibrosis (1 paper, 2025). A final common manifestation of a wide variety of chronic kidney diseases characterized by glomerulosclerosis and tubulointerstitial fibrosis. "To further validate the involvement of hsa_circ_0008925 in the regulation of renal fibrosis through the SRSF6 pathway, we conducted in vivo experiments using a UUO mouse model." (PMID 39799463, 2025). "In our study, we discovered that SRSF6 has a profibrotic role in renal fibrosis, indicating its involvement not only in tumours but also in the progression of renal fibrosis." (PMID 39799463, 2025). "Our findings suggest that hsa_circ_0008925 potentially contributes to the development of renal fibrosis by interacting with SRSF6 proteins." (PMID 39799463, 2025). "Hsa_circ_0008925 promoted renal fibrosis by upregulating the expression of SRSF6 in vitro and in vivo." (PMID 39799463, 2025). "Although the role of SRSF6 in various fibrotic diseases has gradually emerged, its specific involvement in renal fibrosis remains unclear." (PMID 39799463, 2025). "Silencing mmu_circ_0002215 and inhibiting SRSF6 alleviated renal fibrosis in a UUO model in vivo." (PMID 39799463, 2025). "This further validates the involvement of the hsa_circ_0008925/SRSF6 signalling pathway in renal fibrosis and suggests that indacaterol may serve as a novel strategy for treating renal fibrosis through the targeting of SRSF6." (PMID 39799463, 2025). "Inhibiting hsa_circ_0008925/SRSF6 alleviated renal fibrosis in vitro and in vivo." (PMID 39799463, 2025).
T-cell acute lymphoblastic leukemia (1 paper, 2021). Acute lymphoblastic leukemia of T-cell origin. "In T-cell acute lymphoblastic leukemia, SRSF6 inhibits apoptosis by binding to 3’ splice site of CCAR1 exon 22 and promoting exon 15–22 skipping." (PMID 34917618, 2021).